IGF2 (insulin like growth factor 2)
Diseases named in the same sentence as IGF2 in open-access papers (continued):
Sharing a sentence is not in itself a finding about the gene and the disease.
macroglossia (7 papers, 2010 to 2025). The presence of an excessively large tongue, which may be congenital or may develop as a result of a tumor or edema due to obstruction of lymphatic vessels, or it may occur in association with hyperpituitarism or acromegaly. "When birth, further studies displayed that the methylation and expression levels of H19/Igf2 in the NT-CON-M group were significantly higher than those in the NT-CON-N (cloned piglets without macroglossia), NT-TSA-N and IVF groups (P<0.05)." (PMID 25962071, 2015). "Encouragingly, no macroglossia occurred in the NT-TSA group, even the only one deceased cloned piglet, and the imprinting of H19/Igf2 were normal in the NT-TSA group, suggesting that TSA has a correcting effect on genomic imprinting." (PMID 25962071, 2015).
macrosomia (7 papers, 2010 to 2025). "On the other hand, a following study observed that the macrosomia induced by intrauterine hyperglycemia was strongly associated with the cord blood methylation and placenta gene expression status of IGF2/H19." (PMID 37107594, 2023). "The present study also explored the independent association between the IGF2 gene and macrosomia by detecting and comparing the expression levels of IGF2 mRNA/H19 RNA in maternal peripheral blood and fetal cord blood of 26 human pregnancies." (PMID 37152930, 2023). "We also provided the evidence of strong associations between methylation of IGF2/H19 DMRs and macrosomia induced by intrauterine hyperglycemia." (PMID 26840070, 2016). "In order to observe the associations between methylation of IGF2/H19 DMRs and macrosomia induced by intrauterine hyperglycemia, we analyzed the methylation levels of IGF2/H19 DMRs of umbilical cord blood of neonates born to normal and GDM." (PMID 26840070, 2016). "In addition, we explored the independent association between IGF2 gene expression and macrosomia by comparing the expression levels of IGF2 mRNA/H19 RNA in maternal peripheral blood and fetal cord blood of humans." (PMID 37152930, 2023). "Here we hypothesize that alteration in methylation at differentially methylated region of the insulin-like growth factor 2 and H19 is associated with macrosomia induced by intrauterine hyperglycemia." (PMID 26840070, 2016). "Our previous studies also indicated that a high glucose concentration in the context of GDM increased the expression of IGF2 and its imprinted gene (H19) by changing the levels of methylation in the IGF2 and H19 gene promoters, which might be the underlying pathogenic mechanism of macrosomia." (PMID 37152930, 2023). "The gene expression of IGF2 and H19 in cord blood may be associated with macrosomia." (PMID 26840070, 2016). "The mRNA expression of IGF2 showed significant decrease and the H19 RNA showed higher expression in the maternal peripheral blood of the macrosomia group (MM), compared with that in the normal birth weight group (CTRL-M)." (PMID 37152930, 2023). "By controlling for maternal age, height, gestation age, prepregnancy weight, predelivery weight and gestational weight gain, the present study demonstrated that IGF2 expression was an independent factor connected with macrosomia." (PMID 37152930, 2023). "This study also found that in normal mothers with the similar clinical characteristics, IGF2 expression in the maternal peripheral blood and fetal cord blood is an independent factor influencing macrosomia." (PMID 37152930, 2023). "Our previous study indicated that in normal pregnant women, the expression of IGF2 in the placenta and cord blood was significantly higher for women with macrosomia than for women with normal birth weight neonates." (PMID 37152930, 2023). "Compared with that in the fetal cord blood of the normal birth weight group (CTRL-F), the mRNA expression of IGF2 in the fetal cord blood of the macrosomia group (MF) was increased, and the RNA expression of H19 was significantly reduced." (PMID 37152930, 2023). "In addition, we found an independent correlation between IGF2 levels and macrosomia by comparing the expression levels of IGF2/H19 in maternal peripheral blood and fetal cord blood." (PMID 37152930, 2023). "The expression of insulin-like growth factor 2 is significant higher in normal glucose tolerance with macrosomia group (NGT-M) compared to normal glucose tolerance with normal birthweight group (NGT-NBW group) both in placenta and umbilical cord blood." (PMID 26840070, 2016). "Elevated IGF2 levels may be beneficial in stabilizing blood glucose concentrations, such as in the intrauterine hyperglycemic environment in women with GDM, but the consequence of this process affecting weight gain probably leads to macrosomia, which is an adverse pregnancy outcome." (PMID 37152930, 2023).
myocardial infarction (7 papers, 2011 to 2025). Gross necrosis of the myocardium, as a result of interruption of the blood supply to the area, as in coronary thrombosis. "Studies have demonstrated that disruption of SCN function can induce the polarization of macrophages toward an anti-inflammatory phenotype by upregulating insulin-like growth factor 2 (IGF2), thereby improving cardiac repair after myocardial infarction." (PMID 41451215, 2025). "The inhibition of SCN function could improve the inflammatory response after myocardial infarction and promote cardiac repair by upregulating BMAL1 to promote insulin-like growth factor 2 (Igf2) expression and inducing macrophage conversion to an anti-inflammatory phenotype." (PMID 40429770, 2025).
preeclampsia (7 papers, 2012 to 2025). Preeclampsia is a hypertensive disorder of pregnancy that is characterized by new-onset hypertension with proteinuria presenting after 20 weeks of gestation, and depending on mild or severe forms may initially present with severe headache, visual disturbances, and hyperreflexia. "In pregnant women, a positive correlation between plasma IGF-2 concentration and preeclampsia was shown." (PMID 34063412, 2021). "The average methylation level at IGF2 DMR was significantly correlated with preeclampsia even after birth weight, maternal age, gestational age at delivery and fetal gender were adjusted." (PMID 23844573, 2013). "We found that maternal preeclampsia induced a decrease in DNA methylation level at IGF2 DMR in infants." (PMID 23844573, 2013). "The methylation levels at sites 3, 6 and 7 of IGF2 DMR were significantly lower in preeclampsia than normal pregnancy (P=0.045, 0.009 and 0.048, respectively), but the methylation levels at site 4, 9 and 10 did not significantly differ (P>0.05 for all)." (PMID 23844573, 2013). "At the individual gene level, IGF2 but not GNAS has been found to be significantly hypomethylated in cord blood cells associated with maternal preeclampsia." (PMID 25806090, 2015). "Methylation levels at IGF2 DMR were significantly lower in preeclampsia than normal pregnancy." (PMID 23844573, 2013). "Small-for-gestational age (SGA) and preeclampsia, conditions characterized by poor nutrient supply to fetus, induces hypomethylation at IGF2 and GNAS DMRs and altered methylation at DMRs of imprinted genes may subsequently contribute to the development of metabolic diseases in later life." (PMID 25269528, 2014). "Taken together with our previous study reported significant lower methylation in offspring of preeclampsia than normal pregnancy, it indicates that the methylation of IGF2 DMR could be a better biomarker than H19 DMR to evaluated the effect of environmental exposure in early development." (PMID 25269528, 2014). "The average methylation level at the IGF2 DMR was significantly different among normal pregnancy, gestational hypertension and preeclampsia (F=3.242, P=0.042)." (PMID 23844573, 2013). "They found that the average methylation level of IGF2 but not GNAS was significantly lower in the preeclampsia samples." (PMID 25806090, 2015). "In the current investigation, we revealed for the first time that maternal preeclampsia but not gestational hypertension induced a decrease in DNA methylation level at IGF2 DMR in infants." (PMID 23844573, 2013). "In this study, we found that methylation level at IGF2 DMR was negatively correlated with birth weight in normal pregnancy but not in preeclampsia or gestational hypertension." (PMID 23844573, 2013). "However, the effect of GDM, a condition apposite to SGA and preeclampsia, on the methylation at DMRs of IGF2 and GNAS of fetus has not been described yet." (PMID 25269528, 2014). "Furthermore, the methylation levels of IGF2 and DNAS DMRs were not significantly different between mild and severe preeclampsia (P>0.05 for all) (data not shown)." (PMID 23844573, 2013).
steatosis (7 papers, 2016 to 2023). Increased lipid within the cytoplasm of cells. "Hepatic expression of insulin-like growth-factor binding protein (IGFBP)-6—a transport protein for insulin-like growth-factor 2 (IGF2)—was recently reported to be positively associated with steatosis and fibrosis in NAFLD." (PMID 36430499, 2022). "Although IGF2 has been reported to be overexpressed in steatosis and steatohepatitis, a causal role of IGF2 in steatosis development remains elusive." (PMID 27199763, 2016). "Although insulin-like growth factor 2 (IGF2) has been reported to be overexpressed in steatosis and steatohepatitis, a causal role of IGF2 in steatosis development remains elusive." (PMID 27199763, 2016). "The study concluded that IGF2 can play a causal role in steatosis initiation." (PMID 29702590, 2018). "Taken together, our data show that hepatic IGF2 overexpression can lead to an increased lipid droplet formation and free cholesterol accumulation and might therefore play a causal role in steatosis initiation." (PMID 27199763, 2016). "Using in vitro models, wefound that IGF2 was the key overexpressed gene in steatosis, suggesting a possibleassociation between IGF2 and NAFLD." (PMID 33988719, 2021). "Our findings demonstrated that IGF2 was significantly upregulatedin free fatty acid-induced steatosis in HepG2 and AML12 cells." (PMID 33988719, 2021). "SREBF1 target genes, which are also involved in de novo lipid synthesis and steatosis development, were slightly upregulated in IGF2 overexpressing mice supporting lipogenic actions of IGF2." (PMID 27199763, 2016). "In this study we investigated the role of IGF2 in this liver phenotype and showed that loss of IGF2 reduced liver inflammation and fibrosis, but not steatosis, in mice lacking SRSF3 in hepatocytes." (PMID 35615981, 2022). "In summary, steatosis upregulates IGF2 mRNA and protein levels in the liver tissues ofobese mice." (PMID 33988719, 2021). "IGF2, meanwhile, can be a key factor in the development of steatosis that accompanies NAFLD/NASH." (PMID 29702590, 2018). "Furthermore, free cholesterol, which can be stored in LDs and has been reported to be critical for steatosis progression, was elevated in Igf2 overexpressing mice." (PMID 27199763, 2016). "Aim of our study was to decipher the role of IGF2 in steatosis development." (PMID 27199763, 2016). "IGF2 signaling can be involved in the transition of steatosis and steatohepatitis to HCC due to downregulation of the tumor suppressor PTEN by IGF2." (PMID 27199763, 2016). "Igf2 transgenic mice show fetal overgrowth and neonatal lethality and can therefore not be used to study the role of IGF2 in steatosis." (PMID 27199763, 2016). "Up to now it is not completely clear, what distinguishes the effects of IGF2 from the ones of IGF1 in steatosis." (PMID 27199763, 2016). "Scharlach Red staining showed that IGF2 induced features of mild steatosis without any specific zonation of lipid accumulation." (PMID 27199763, 2016). "The role of IGF2 in thepathophysiology of steatosis was not evaluated." (PMID 33988719, 2021).
amyloid (6 papers, 2014 to 2025). "For example, IGF2 has been shown to reduce amyloidosis, stimulate neurogenesis and synaptogenesis, further improving cognitive functions in AD." (PMID 40713750, 2025). "Most importantly, we reported that intracerebroventricular IGF2 infusion ameliorates the amyloidosis and the cholinergic defect in the APP.PS1 mice." (PMID 28103298, 2017). "Insulin-like growth factor-2 (IGF-2) was reported to attenuate memory decline and amyloid plaque formation in AD mouse model by activating the PI3K/AKT/CREB signaling pathway, and insulin has been observed to promote neuron growth and synapse formation through the PI3K signaling pathway." (PMID 34277597, 2021). "Additionally, infusion of IGF2 in the APP.PS1 mouse model of AD ameliorated amyloidosis." (PMID 38315685, 2024).
bipolar disorder (6 papers, 2019 to 2024). A disorder of the brain that causes unusual shifts in mood, energy, activity levels and the ability to carry out day-to-day tasks. "Bearing this in mind, it would be interesting to study whether there is an imbalance in IGF-2 levels at the onset of bipolar disorder." (PMID 38720780, 2024). "It was also suggested that an effective treatment of lithium for bipolar disorder could be partially explained by reduced DNA methylation at the IGF2/H19 imprinting control region in mouse embryonic and neural stem cells." (PMID 35178127, 2022).
colorectal adenoma (6 papers, 2009 to 2024). An adenoma that arises from the colon or rectum. "Several studies have elucidated that serum level and loss of imprinting of IGF2 were associated with advanced colorectal adenoma and poor prognosis in advanced stages of CRC, respectively." (PMID 31664994, 2019). "Complete loss of methylation at the IGF2 differentially methylated region (DMR) results in biallelic expression of IGF2 and is associated with an increased risk of colorectal adenoma." (PMID 19924280, 2009). "Interestingly, colorectal adenomas, a precancerous condition, showed similar levels of IGF2 methylation compared to tumour tissues." (PMID 37213278, 2023). "The findings from the GEO and TCGA datasets indicate that IGF2 methylation in tissues can discern colorectal adenomas or CRCs from normal intestinal mucosa, which also suggests that IGF2 methylation may prove valuable during CRC screening for early cancer detection." (PMID 37213278, 2023). "Among the down-regulated genes, the researchers identified IGF2, SOCS1, MLH1, and CACNA1G as being significantly decreased in colorectal adenoma tissue samples." (PMID 38874740, 2024).
idiopathic pulmonary fibrosis (6 papers, 2021 to 2025). Idiopathic pulmonary fibrosis (IPF) is a nonneoplastic pulmonary disease that is characterized by the formation of scar tissue within the lungs in the absence of any known cause. "Some studies have shown that the IGF-2 P3 promoter is activated in a pathological model of SSc-related pulmonary fibrosis, which improves IGF-2 mRNA in SSc lung fibroblasts." (PMID 39695964, 2024). "In recent years, high IGF-2 expression has been found in various fibrotic diseases such as liver cirrhosis, idiopathic pulmonary fibrosis, and hypertrophic scars." (PMID 36358907, 2022). "In addition, IGF2 promotes the proliferation of lung fibroblasts and inhibits their apoptosis to increase pulmonary fibrosis." (PMID 39744430, 2025). "IGF-2 also promotes pulmonary fibrosis through other mechanisms." (PMID 36358907, 2022). "IGF2 promotes fibroblast proliferation and inhibits apoptosis through PI3K/AKT and mitogen-activated extracellular kinase (MEK)/JNK pathways and increases extracellular matrix synthesis to promote pulmonary fibrosis." (PMID 39744430, 2025).
Impaired glucose tolerance (6 papers, 2011 to 2023). An abnormal resistance to glucose, i.e., a reduction in the ability to maintain glucose levels in the blood stream within normal limits following oral or intravenous administration of glucose. "Another commonly observed epigenetic pattern is the alteration in IGF2 methylation in the male germline, which results in β-cell dysfunction and impaired glucose tolerance in the offspring." (PMID 35328389, 2022).
ischemic stroke (6 papers, 2013 to 2026). A stroke disorder caused by obstruction of blood flow to the brain, due to thrombotic (local blood clot formation) or embolic (due to a blood clot or other material traveling from another site) event. "Although no much evidence in the association between IGF2 and the risk of ischemic stroke yet, IGF2 might contribute to vascular remodeling and neovascularization by enhancing the recruitment and incorporation of endothelial progenitor cells into areas of ischemic injury." (PMID 31262327, 2019).
lymph node metastasis (6 papers, 2009 to 2021). "The N stage in TNM staging, i.e., the occurrence of lymph node metastasis, was associated with IGF-2 gene methylation frequency." (PMID 23554734, 2012). "LOI of IGF2 in tumours was also associated with the lymph node metastasis (LNM) (OR = 4.5, 95% CI = 1.084-18.689, p = 0.038)." (PMID 19737423, 2009). "The study found that the expression of IGF-2 was related to histological grade, lymph node metastasis and ER status." (PMID 22662119, 2012). "And we found patients with LOI of IGF2 in their tumour had higher increased risk of the lymph node metastasis than those without (OR = 4.5, 95%CI = 1.084-18.689, p = 0.038)." (PMID 19737423, 2009). "Specifically, the IGF-2 gene in cancer patients with lymph node metastasis had a methylation frequency of 46.3%, which was significantly lower than that in patients without lymph node metastasis (17.2%, P < 0.05)." (PMID 23554734, 2012). "The rate of IGF-2 gene expression in cases with lymph node metastasis was higher than in patients without lymph node metastasis." (PMID 22662119, 2012). "The hypomethylation rate of the IGF-2 gene in cancer tissues was significantly higher in patients with lymph node metastasis than in those without lymph node metastasis (46.3% vs 17.2%, P = 0.018)." (PMID 23554734, 2012).
malignant mesothelioma (6 papers, 2019 to 2023). A malignant neoplasm of the pleura or peritoneum, arising from mesothelial cells. "In malignant mesothelioma cells, upon autocrine IGF2 stimulation, IR-A phosphorylates EphB4 at tyrosine 987, thus maintaining EphB4 steady-state levels." (PMID 34440844, 2021). "We identified insulin-like growth factor 2 mRNA binding protein 3 (IGF2BP3) as one of the significantly upregulated genes in malignant mesothelioma." (PMID 35127504, 2021).
malnutrition (6 papers, 2012 to 2024). Inadequate nutrition resulting from poor diet, malabsorption, or abnormal nutrient distribution. "Given that IGF1 and IGF2 levels are gold standards for identifying malnutrition, and that they are major upstream regulators of the PI3K-AKT signaling pathway." (PMID 37872623, 2023). "Compared with AFG, the decreased transcription levels of Myf-5, MRF4 as well as IGF-2 in most of tested positional muscle tissues of GFG, could be induced by malnutrition." (PMID 29632496, 2018).
metastatic tumors (6 papers, 2013 to 2023). "Compared to that in primary CRC, the expression level of IGF2 in CRC metastatic tumors (mainly liver metastases) changes to a greater extent, and its expression can be both high and low." (PMID 34422629, 2021). "Up-regulation of miR-483-5p in metastatic tumors corresponded to the amplification of IGF2 (insulin-like growth factor 2) mRNA due to their co-expression from the same locus." (PMID 33810219, 2021). "H19 is a paternally imprinted lncRNA antisense to the insulin-like growth factor 2 (IGF2) locus which exhibits loss of imprinting and very strong up-regulation in a wide range of metastatic neoplasms." (PMID 24346158, 2014). "Moreover, we found that CAFs from metastatic tumors had higher IGF-2 gene expression, and we detected the same after co-culture with cell lines." (PMID 33114046, 2020). "Finally, we also observed that higher IGF2 gene expression in CAFs from metastatic tumors remained increased after co-culture with MCF-7 or MDA-MB-231." (PMID 33114046, 2020).